DNTTIP2 (deoxynucleotidyltransferase terminal interacting protein 2)
Description:
Regulates the transcriptional activity of DNTT and ESR1. May function as a chromatin remodeling protein. Part of the small subunit (SSU) processome, first precursor of the small eukaryotic ribosomal subunit. During the assembly of the SSU processome in the nucleolus, many ribosome biogenesis factors, an RNA chaperone and ribosomal proteins associate with the nascent pre-rRNA and work in concert to generate RNA folding, modifications, rearrangements and cleavage as well as targeted degradation of pre-ribosomal RNA by the RNA exosome.
Synonyms: LPTS-RP2; TdIF2; ERBP; HSU15552; FCF2
Tractability: Small molecule: a structure with a bound ligand is known. PROTAC: UniProt records ubiquitination sites on it; ubiquitination databases record sites on it; its protein half-life has been measured.
Gene: Protein-coding gene on chromosome 1 (93,866,284 to 93,879,918, reverse strand). Ensembl gene ENSG00000067334.
Subcellular location: Nucleus; Nucleus, nucleolus
Subcellular location (Human Protein Atlas): Nucleoli; Nucleoli rim; Mitotic chromosome; Nucleoplasm
Gene Ontology:
Molecular function: protein binding; RNA binding
Biological process: ribosomal small subunit biogenesis; maturation of SSU-rRNA; RNA processing
Cellular component: nucleolus; nucleoplasm; nucleus; small-subunit processome
Genetic constraint (gnomAD): Loss-of-function variants: 39 observed, 52.18 expected, observed/expected ratio (o/e) 0.75, 90% interval 0.58 to 0.98. The upper end of that interval is the gene's LOEUF score, 0.98, which puts it in group 4 of 6, group 1 being the genes least tolerant of losing a copy. Missense variants: 779 observed, 807.22 expected, observed/expected ratio (o/e) 0.97, 90% interval 0.91 to 1.02. Synonymous variants: 289 observed, 289.02 expected, observed/expected ratio (o/e) 1, 90% interval 0.91 to 1.1.
Homologues: Orthologues: chimpanzee DNTTIP2 (99% identical), macaque DNTTIP2 (97% identical), dog DNTTIP2 (73% identical), pig DNTTIP2 (73% identical), rabbit DNTTIP2 (73% identical), mouse Dnttip2 (61% identical), rat Dnttip2 (59% identical), zebrafish dnttip2 (31% identical), Drosophila melanogaster CG1142 (11% identical), Caenorhabditis elegans Y49F6B.2 (10% identical).
Diseases named in the same sentence as DNTTIP2 in open-access papers:
DNTTIP2 is named in the same sentence as 11 diseases in open-access papers, as found by Europe PMC text mining. Sharing a sentence is not in itself a finding about the gene and the disease. The quoted sentences say what the papers report.
acute myeloid leukemia (1 paper, 2025). Acute myeloid leukemia (AML) is a group of neoplasms arising from precursor cells committed to the myeloid cell-line differentiation. "Additionally, elevated DNTTIP2 expression has been observed in pediatric acute myeloid leukemia as one of the potential hub genes." (PMID 40577282, 2025).
fibrosarcoma (1 paper, 2025). A malignant mesenchymal fibroblastic neoplasm affecting the soft tissue and bone. "Notably, WDR75 showed the strongest association with rapidly accelerated fibrosarcoma (RAF), while DNTTIP2 and BRIX1 were most closely related to CTLA4." (PMID 40577282, 2025).
glioma (1 paper, 2025). A benign or malignant brain and spinal cord tumor that arises from glial cells (astrocytes, oligodendrocytes, ependymal cells). "The amplification of DNTTIP2 is associated with poor prognosis in glioma patients, and its hypermethylation is also linked to unfavorable outcomes, highlighting its potential as a biomarker and therapeutic target." (PMID 40577282, 2025).
ischemic stroke (1 paper, 2020). A stroke disorder caused by obstruction of blood flow to the brain, due to thrombotic (local blood clot formation) or embolic (due to a blood clot or other material traveling from another site) event. "The literature examining the DNTTIP2 is scarce, but in a recent GWAS, the DNTTIP2 gene has been linked to ischemic stroke, an outcome potentially linked to the PUFA modulations." (PMID 31991592, 2020).
pancreatic cancer (1 paper, 2025). "In the context of cancer, DNTTIP2 has been shown to have a significant role in regulating the cell cycle, particularly in pancreatic cancer (PDAC)." (PMID 40577282, 2025).
tumor (2 papers, 2018 to 2025). "Additionally, DNTTIP2 is involved in the IL6/JAK/STAT3 signaling pathway, which is key to tumor growth and immune evasion." (PMID 40577282, 2025).
DNTTIP2 also shares sentences with these, for which no sentence is quoted: cancer (2 papers); hepatocellular carcinoma (1); invasive breast carcinoma (1); migraine (1); pertussis (1).